OR10D3 (olfactory receptor family 10 subfamily D member 3)
Description:
Odorant receptor.
Synonyms: OR10D3P; HTPCRX09
Tractability: Antibody: UniProt places it where antibodies can reach, with high confidence; UniProt predicts a signal peptide or a membrane-spanning region; its Gene Ontology location is reachable by antibodies, with medium confidence.
Gene: Protein-coding gene on chromosome 11 (124,183,345 to 124,188,780, forward strand). Ensembl gene ENSG00000197309.
Subcellular location: Cell membrane
Pathways (Reactome):
Sensory Perception: Expression and translocation of olfactory receptors
Gene Ontology:
Molecular function: olfactory receptor activity; G protein-coupled receptor activity
Biological process: detection of chemical stimulus involved in sensory perception of smell; G protein-coupled receptor signaling pathway
Cellular component: plasma membrane; membrane
Homologues: Orthologues: chimpanzee OR10D3 (99% identical), macaque OR10D3 (96% identical), dog OR10D3 (91% identical), rabbit OR10D3 (90% identical), mouse Or10d3 (89% identical), pig OR10D3 (88% identical), rat Or10d3 (88% identical). Paralogues in human: OR10G7 (53% identical), OR10G4 (52% identical), OR10G9 (51% identical), OR10G2 (50% identical), OR10G6 (49% identical), OR10G8 (49% identical), OR10G3 (48% identical), OR10S1 (46% identical), OR10A6 (45% identical), OR10A7 (45% identical), OR2G6 (45% identical), OR2B2 (44% identical), and 80 more.
Diseases named in the same sentence as OR10D3 in open-access papers:
OR10D3 is named in the same sentence as 1 disease in open-access papers, as found by Europe PMC text mining. Sharing a sentence is not in itself a finding about the gene and the disease.
OR10D3 shares sentences with these, for which no sentence is quoted: breast carcinoma (1 paper).